CAMK2B (calcium/calmodulin dependent protein kinase II beta)
Description:
Calcium/calmodulin-dependent protein kinase that functions autonomously after Ca(2+)/calmodulin-binding and autophosphorylation, and is involved in dendritic spine and synapse formation, neuronal plasticity and regulation of sarcoplasmic reticulum Ca(2+) transport in skeletal muscle. In neurons, plays an essential structural role in the reorganization of the actin cytoskeleton during plasticity by binding and bundling actin filaments in a kinase-independent manner. This structural function is required for correct targeting of CaMK2A, which acts downstream of NMDAR to promote dendritic spine and synapse formation and maintain synaptic plasticity which enables long-term potentiation (LTP) and hippocampus-dependent learning. In developing hippocampal neurons, promotes arborization of the dendritic tree and in mature neurons, promotes dendritic remodeling. Also regulates the migration of developing neurons. Participates in the modulation of skeletal muscle function in response to exercise. In slow-twitch muscles, is involved in regulation of sarcoplasmic reticulum (SR) Ca(2+) transport and in fast-twitch muscle participates in the control of Ca(2+) release from the SR through phosphorylation of triadin, a ryanodine receptor-coupling factor, and phospholamban (PLN/PLB), an endogenous inhibitor of SERCA2A/ATP2A2. In response to interferon-gamma (IFN-gamma) stimulation, catalyzes phosphorylation of STAT1, stimulating the JAK-STAT signaling pathway (By similarity). Phosphorylates reticulophagy regulator RETREG1 at 'Ser-151' under endoplasmic reticulum stress conditions which enhances RETREG1 oligomerization and its membrane scission and reticulophagy activity.
Synonyms: CAM2; CAMK2; CAMKB; CaMKIIβ; CaMKIIbeta; MRD54
Tractability: Small molecule: a structure with a bound ligand is known; a high-quality ligand is known; it belongs to a druggable protein family. Antibody: UniProt places it where antibodies can reach, with high confidence. PROTAC: ubiquitination databases record sites on it; its protein half-life has been measured; a small molecule that binds it is known.
Target class: CAMK protein kinase CAMK2 family; Protein Kinase; Enzyme; CAMK protein kinase group; Kinase
Gene: Protein-coding gene on chromosome 7 (44,209,993 to 44,334,577, reverse strand). Ensembl gene ENSG00000058404.
Subcellular location: Cytoplasm, cytoskeleton; Cytoplasm, cytoskeleton, microtubule organizing center, centrosome; Sarcoplasmic reticulum membrane; Synapse
Subcellular location (Human Protein Atlas): Plasma membrane; Primary cilium tip; Primary cilium transition zone; Principal piece; Calyx; Cell Junctions; Connecting piece; End piece; Perinuclear theca
Pathways (Reactome):
Neuronal System: Assembly and cell surface presentation of NMDA receptors; CREB1 phosphorylation through the activation of CaMKII/CaMKK/CaMKIV cascasde; Long-term potentiation; Negative regulation of NMDA receptor-mediated neuronal transmission; Ras activation upon Ca2+ influx through NMDA receptor; Trafficking of AMPA receptors; Unblocking of NMDA receptors, glutamate binding and activation
Disease: Dengue Virus-Host Interactions; Paradoxical activation of RAF signaling by kinase inactive BRAF; Signaling by BRAF and RAF1 fusions; Signaling by RAF1 mutants; Signaling by moderate kinase activity BRAF mutants; Signaling downstream of RAS mutants
Signal Transduction: CaMK IV-mediated phosphorylation of CREB; RAF activation; RAF/MAP kinase cascade
Muscle contraction: Ion homeostasis; Phase 0 - rapid depolarisation
Cellular responses to stimuli: HSF1-dependent transactivation
Immune System: Interferon gamma signaling
Transport of small molecules: Ion transport by P-type ATPases
Gene Ontology:
Molecular function: calcium/calmodulin-dependent protein kinase activity; identical protein binding; protein binding; protein homodimerization activity; protein serine kinase activity; calmodulin binding; ATP binding; protein kinase activity
Biological process: protein autophosphorylation; regulation of neuron migration; long-term synaptic potentiation; positive regulation of dendritic spine morphogenesis; positive regulation of neuron projection development; positive regulation of synapse maturation; protein phosphorylation; regulation of calcium ion transport; regulation of dendritic spine development; regulation of long-term neuronal synaptic plasticity; regulation of neuronal synaptic plasticity; regulation of protein localization to plasma membrane; regulation of skeletal muscle adaptation; regulation of synapse structural plasticity; signal transduction
Cellular component: calcium- and calmodulin-dependent protein kinase complex; cytoplasm; cytosol; endocytic vesicle membrane; endoplasmic reticulum membrane; neuron projection; nucleoplasm; postsynaptic density; synapse; centrosome; cytoskeleton; sarcoplasmic reticulum membrane
Genetic constraint (gnomAD): Loss-of-function variants: 24 observed, 75.03 expected, observed/expected ratio (o/e) 0.32, 90% interval 0.23 to 0.45. The upper end of that interval is the gene's LOEUF score, 0.45, which puts it in group 1 of 6, group 1 being the genes least tolerant of losing a copy. Missense variants: 508 observed, 762.41 expected, observed/expected ratio (o/e) 0.67, 90% interval 0.62 to 0.72. Synonymous variants: 336 observed, 298.84 expected, observed/expected ratio (o/e) 1.12, 90% interval 1.03 to 1.23.
Homologues: Orthologues: chimpanzee CAMK2B (100% identical), macaque CAMK2B (99% identical), mouse Camk2b (97% identical), guinea pig CAMK2B (90% identical), pig CAMK2B (84% identical), tropical clawed frog camk2b (82% identical), rat Camk2b (81% identical), dog CAMK2B (80% identical), zebrafish camk2b1 (76% identical), zebrafish camk2b2 (52% identical). Paralogues in human: CAMK2G (72% identical), CAMK2D (67% identical), CAMK2A (61% identical), CAMK1G (21% identical), CAMK1D (21% identical), CAMK1 (21% identical), DCLK2 (21% identical), DCLK1 (20% identical), PHKG2 (20% identical), PNCK (20% identical), PHKG1 (19% identical), CAMKV (18% identical), and 10 more.
Diseases named in the same sentence as CAMK2B in open-access papers:
CAMK2B is named in the same sentence as 85 diseases in open-access papers, as found by Europe PMC text mining. Sharing a sentence is not in itself a finding about the gene and the disease. The quoted sentences say what the papers report.
breast carcinoma (11 papers, 2015 to 2025). "Hypermethylation of CAMK2B has been reported in breast cancer compared with normal breast tissue, indicating that promoter methylation of CAMK2B is an epigenetic marker for breast cancer." (PMID 40836964, 2025). "CAMK2B silencing correlates with breast cancer progression and functions as a tumor suppressor in renal papillary cell carcinoma." (PMID 39796709, 2024). "Furthermore, CAMK2B contributes to the growth of various tumor types, including papillary renal cell carcinoma, human neuroblastoma, and breast cancer." (PMID 41050075, 2025). "We next assessed whether CaMKII expression is associated with breast cancer patient outcome by examining CAMK2A, CAMK2B, CAMK2G and CAMK2D mRNA expression in a publically available 1881-sample breast cancer data set25." (PMID 27605043, 2016).
depression (8 papers, 2014 to 2026). "The correlation of Adcy9, Apc, Camk2b, Camk2g, and Ctnnd2 with the pathological mechanisms of depression was first reported in the present work." (PMID 34520625, 2021).
Intellectual disability (8 papers, 2018 to 2025). "Recently, it has been reported that de novo mutations in the protein kinase genes CAMK2A and CAMK2B cause intellectual disability and neurodevelopmental disorders." (PMID 32560273, 2020). "Interestingly, genes connecting pairs of 16p11.2 genes were enriched for genes intolerant to functional variation, such as ASH1L, a histone methyltransferase activator and autism candidate gene, and CAMK2B, a protein kinase gene causative for intellectual disability." (PMID 33819264, 2021). "Since the identification of CDK13, CAMK2B and RALA as syndromic, intellectual disability genes, we assume that the involvement of CDK13, CAMK2B and RALA genes in the deletion of our patient explains the presence and the severity of the intellectual disability." (PMID 34828280, 2021). "Following the reduced expression level of CAMK2B, a compensatory increase in CAMK2A expression can counteract this decline, exemplified by the impact of CAMK2A and CAMK2B deletion on brain neurodevelopment, ultimately leading to intellectual disability." (PMID 41050075, 2025).
papillary renal cell carcinoma (5 papers, 2022 to 2025). A rare subtype of renal cell carcinoma, arising from the renal tubular epithelium and showing a papillary growth pattern, which typically manifests with hematuria, flank pain, palpable abdominal mass or nonspecific symptoms, such as fatigue, weight loss or fever. "CAMK2B regulates the microenvironmental remodeling of renal papillary cell carcinoma, which has an anti-tumor effect." (PMID 36353119, 2022).
schizophrenia (5 papers, 2014 to 2025). A major psychotic disorder characterized by abnormalities in the perception or expression of reality. "One particular CAMK protein, Camk2B, is expressed widely in the CNS, and levels of CAMK2B mRNA were found to be upregulated 2-fold in the frontal cortex of post-mortem schizophrenia patient brains compared to control brains." (PMID 24672476, 2014).
Ataxia (4 papers, 2014 to 2025). Ataxia refers to impaired coordination of voluntary muscle movement. "To address a potential effect of CaMK2 deregulation or ataxia on NMJ integrity, we employed a morphometric analysis of NMJs in Camk2bΔE2/ΔE2mice." (PMID 40295530, 2025).
autism (4 papers, 2018 to 2025). Persistent deficits in social interaction and communication and interaction as well as a markedly restricted repertoire of activity and interest as well as repetitive patterns of behavior. "We identified 178 phosphorylation sites with higher phosphorylation level on the left striatum and 124 on the right among 142 autism-related proteins, including ANK2, CaMK2B and SHANK3." (PMID 40890295, 2025).
epilepsy (4 papers, 2020 to 2025). A brain disorder characterized by episodes of abnormally increased neuronal discharge resulting in transient episodes of sensory or motor neurological dysfunction, or psychic dysfunction. "CAMK2B might also regulate Ca2+ influx, which would initiate a series of rapid depolarization processes to make cells unusually excited, thus leading to epilepsy." (PMID 37567882, 2023).
glioblastoma (4 papers, 2017 to 2021). The most malignant astrocytic tumor (WHO grade IV). "Another study also reported that CAMK2B played an important role in glioblastoma multiforme using bioinformatics analysis on publicly available datasets." (PMID 31827401, 2019). "In addition, we also identified key genes, including MMP9, CD44, CDC42, COL1A1, COL1A2, CAMK2A, and CAMK2B, as potential target genes for diagnosing glioblastoma." (PMID 28191466, 2017).
glioma (4 papers, 2017 to 2025). A benign or malignant brain and spinal cord tumor that arises from glial cells (astrocytes, oligodendrocytes, ependymal cells). "This study aims to explore the role of calcium/calmodulin-dependent protein kinase IIβ (CAMK2B) in regulating the malignant progression of glioma cells, as well as the molecular mechanisms underlying these malignant behaviors." (PMID 41050075, 2025). "For example, liquid biopsy, emerging sequencing technologies, and methylation detection provide new approaches for exploring the role of CAMK2B in glioma and hold significant potential as gene diagnostic tools." (PMID 41050075, 2025). "Despite these findings, the molecular mechanism underlying the clinical significance of CAMK2B in glioma remains largely unknown." (PMID 41050075, 2025). "Given that CAMK2B promotes the progression of glioma through the activation of the MAPK kinase signaling pathway, indirectly targeting CAMK2B using MAPK kinase inhibitors is a potential therapeutic strategy for glioma." (PMID 41050075, 2025). "The expression levels of CAMK2B in transfected glioma cells (U251) were assessed using qRT-PCR and Western blot." (PMID 41050075, 2025). "We used Transwell and wound healing assays to assess the impact of activated CAMK2B on the invasive and migrative activity of glioma cells." (PMID 41050075, 2025). "Knockdown of CAMK2B was achieved by transfecting a siRNA plasmid targeting CAMK2B into the glioma cell lines." (PMID 41050075, 2025). "The glioma cells were categorized into two groups: the CAMK2B overexpression group (group OE-CAMK2B) and the blank control group transfected with empty plasmids (group OE-NC)." (PMID 41050075, 2025). "To examine the effects of CAMK2B activation on the proliferation of glioma cells, we overexpressed CAMK2B through the transfection of plasmid into U251 and U87 cells, with transfection of empty plasmids serving as a blank control." (PMID 41050075, 2025). "The results revealed that the expression level of CAMK2B was downregulated in glioma cells by about 40%." (PMID 41050075, 2025). "The correlation between CAMK2B expression in gliomas and patient prognosis was analyzed using immunohistochemistry, quantitative reverse transcription polymerase chain reaction (qRT-PCR), and western blot." (PMID 41050075, 2025). "By blocking its kinase activity, the key role of CAMK2B in the proliferation, migration, and invasion of glioma cells can be inhibited." (PMID 41050075, 2025). "Based on transcriptome data obtained from the GEPIA database, we found that the expression level of CAMK2B was lower in glioma tissues compared to normal brain tissues." (PMID 41050075, 2025). "This viewpoint represents a promising direction for future investigations aimed at elucidating the role of CAMK2B in glioma pathogenesis." (PMID 41050075, 2025). "The results revealed that CAMK2B expression levels were decreased in tissues of glioma at high grades." (PMID 41050075, 2025). "In summary, we have demonstrated that the expression level of CAMK2B in gliomas is significantly lower compared to that in normal brain tissues." (PMID 41050075, 2025). "CAMK2B inhibits glioma proliferation, invasion, and migration through the Ras/Raf/MEK/ERK signaling pathway." (PMID 41050075, 2025). "In this study, we preliminarily verified the relationship between CAMK2B and the malignant progression of glioma, and demonstrated through a series of experiments that this relationship is established via the Ras/Raf/MEK/ERK signaling pathway." (PMID 41050075, 2025). "We analyzed CAMK2B expression in normal brain tissue and grade I-IV glioma tissue using the IHC technique." (PMID 41050075, 2025). "Conversely, knockdown of CAMK2B using siRNA-CAMK2B significantly enhanced the proliferative, invasive, and migratory capabilities of glioma cells in both in vitro and in vivo settings, enhancing these abilities by 1.5 to 3 times." (PMID 41050075, 2025).
glioma (continued). "In GBM-glioma subtype the order of expression from highest to lowest was as follows: CaMK2G > CaMK2B ≥ CaMK2A > CaMK2D." (PMID 28663722, 2017). "Additionally, the mRNA levels quantified using the qRT-PCR and protein levels quantified using the Western blot yielded similar results, indicating that CAMK2B expression was lower in three glioma cells compared to the astrocytes." (PMID 41050075, 2025). "The expression of CAMK2B varies across different cancer types, CAMK2B has been reported as downregulated in gliomas and may act as a tumor suppressor in some contexts (Johansson, Göransson & Westermark, 2005)." (PMID 41424711, 2025). "Notably, CAMK2B exerts its effects on the biological process of glioma by activating the Ras/Raf/MEK/ERK signaling pathway." (PMID 41050075, 2025). "Furthermore, based on the KEGG database, we discovered that CAMK2B can exert an influence on the growth and proliferation of glioma cells via the PI3K/AKT/mTOR signaling pathway." (PMID 41050075, 2025). "Specifically, CAMK2B is downregulated in glioma, which indicates that it may serve as a potential prognostic marker and therapeutic target." (PMID 41050075, 2025). "Therefore, our future research will focus on this causal relationship to further improve the understanding of the mechanism by which CAMK2B influences the malignant progression of glioma." (PMID 41050075, 2025). "Consequently, this study aims to elucidate the role of CAMK2B in the pathogenesis of glioma, as well as the signaling pathways it exerts its therapeutic effects, by conducting in vitro and in vivo experiments." (PMID 41050075, 2025). "Notably, overexpression of CAMK2B in glioma cells led to an approximate 40% reduction in proliferative capacity and a 60–70% decrease in invasive and migratory abilities, compared to control glioma cells." (PMID 41050075, 2025). "Moreover, CAMK2A, a homolog of CAMK2B, has been reported to significantly suppress glioma proliferation and metastasis induced by miR-3200-3p when it is overexpressed." (PMID 41050075, 2025). "Furthermore, the study explored the role of CAMK2B in glioma cell proliferation, invasion, and migration using cell counting kit-8 (CCK-8), 5-Ethynyl-2′-deoxyuridine (EdU), wound healing, transwell, and in vivo tumor xenograft assays." (PMID 41050075, 2025). "Furthermore, CAMK2B expression was significantly lower in glioma tissues and cells compared to both normal brain tissue and human astrocyte cell lines." (PMID 41050075, 2025). "Our study into CAMK2B as a potential therapeutic target for glioma has revealed that therapeutic strategies involving RNA-based therapies, chemical inhibitory compounds, and indirect targeting using MAPK kinase inhibitors possess distinct benefits and limitations." (PMID 41050075, 2025). "Additionally, we have revealed that CAMK2B levels exert a profound influence on the proliferative, invasive, and migratory capabilities of glioma cells both in vitro and in vivo." (PMID 41050075, 2025). "Consequently, this study investigated whether CAMK2B (a member of the CAMK family) exerts similar impacts on glioma invasion and migration." (PMID 41050075, 2025). "Therefore, we hypothesize that CAMK2B may modulate glioma progression through the PI3K/AKT/mTOR signaling pathway." (PMID 41050075, 2025). "Consequently, we hypothesize that CAMK2B possesses the ability to regulate the invasive capacity of the glioma cells." (PMID 41050075, 2025). "Furthermore, Ca2+, as a potential upstream regulator of CAMK2B, may provide valuable avenues for future investigations into the role of CAMK2B in the malignant progression of glioma." (PMID 41050075, 2025). "We have also established that CAMK2B exerts its influence through the Ras/Raf/MEK/ERK signaling pathway, thereby presenting novel therapeutic targets and avenues for future research in the diagnosis and treatment of glioma." (PMID 41050075, 2025).
glioma (continued). "The PCR results revealed that suppressing the expression of CAMK2B in the U251 glioma cell line did not significantly alter the expression patterns of CAMK1D." (PMID 41050075, 2025). "Knockdown of CAMK2B with siRNA resulted in an increased expression level of Ras, p-Raf, p-MEK, and p-ERK; these effects were inhibited by the Ras inhibitor Salirasib, indicating that Salirasib can inhibit the proliferation of glioma cells both in vivo and in vitro." (PMID 41050075, 2025).
Obesity (4 papers, 2017 to 2024). Accumulation of substantial excess body fat. "Functional studies in mice have demonstrated that Camk2b−/− are susceptible to obesity and that the enzyme Camk2b is translated into, CaMKII, is involved in the hepatic insulin resistance that occurs with obesity." (PMID 34849860, 2021).